GATA4 (GATA binding protein 4)
Diseases named in the same sentence as GATA4 in open-access papers (continued):
Sharing a sentence is not in itself a finding about the gene and the disease.
ventricular septal defect (26 papers, 2011 to 2026). The presence of a defect (opening) in the septum that separates the two ventricles of the heart. "We previously reported that a heterozygous G296S missense mutation of GATA4 caused atrial and ventricular septal defects and pulmonary valve stenosis in humans." (PMID 22589735, 2012). "The aim of this study was to examine how somatic mutations of the GATA4 gene contributed to the genesis of ventricular septal defect (VSD)." (PMID 23554720, 2011). "We describe the findings of genotyping the polymorphisms in the MTRR, GATA4, VEGF and ISL1 genes in Pakistani children with isolated ventricular septal defects." (PMID 33757570, 2021). "GATA4 has been identified as causative factors of familial ASD and VSD, and found to play a predominant role in the pathogenesis of both atrial and ventricular septal defects." (PMID 25928801, 2015). "GATA4-NKX2-5 physical and functional interactions have been confirmed in both mouse models and human cardiomyocytes, with human genetic studies showing digenic inheritance patterns involving GATA4 and NKX2-5 variants in families with atrial and ventricular septal defects." (PMID 40917916, 2025). "We previously reported a truncated GATA4 protein lacking C-terminus induced by p.S335X mutation in cardiomyocyte from ventricular septal defect (VSD) patients." (PMID 34545275, 2021). "Knockout mice for Tbx1 or double heterozygous knockout mice for Gata4 and Gata6 exhibit fetal nuchal edema with ventricular septal defect (VSD) and persistent truncus arteriosus (PTA)." (PMID 36111337, 2022). "We previously detected a p.S335X mutation in GATA4 in ventricular septal defect (VSD) patients, which could lead to truncated GATA4 protein lacking a conservative region at C-terminus." (PMID 34545275, 2021). "ASD may be isolated or associated with other CHDs, such as pulmonary valve stenosis (PVS), ventricular septal defect (VSD) and conduction defects, one of the study found that GATA4 genetic variations are associated with ASD, TOF and VSD in South Indian patients." (PMID 33413087, 2021). "Strikingly, the absence of GATA4 in NCCs induced severe cardiac defects with a prominent ventricular septal defect (VSD) and enlarged heart." (PMID 29523871, 2018).
ovarian carcinoma (23 papers, 2009 to 2025). A malignant neoplasm originating from the surface ovarian epithelium. "Alterations in the expression of GATA4 have been associated with different types of cancer, including ovarian cancer." (PMID 38408933, 2024). "The loss of GATA4 expression due to promoter hypermethylation has been reported in primary colorectal, gastric, esophageal, lung, and ovarian cancers." (PMID 31405379, 2019). "In ovarian cancer loss of GATA4 precedes loss of GATA6 expression and candifferentiate between histological subtypes." (PMID 26953528, 2016). "Loss of GATA4 expression due to promoter hypermethylation has been reported in primary colorectal, gastric, esophageal, lung and ovarian cancer." (PMID 23320456, 2013). "The observations from human ovarian cancer tissues suggests that loss of GATA4 expression often precedes the loss of GATA6, and the loss of GATA6, correlated with the loss of Dab2, associates with epithelial morphological transformation." (PMID 19649254, 2009). "Recent studies suggest the loss of the transcription factor GATA6 and GATA4 in ovarian cancer may account for the loss of epithelial characteristics and may be the underlying mechanism of “dedifferentiation” of ovarian cancer cells." (PMID 19649254, 2009). "Thus, loss of GATA4 appears to be more prevalent than loss of GATA6 in ovarian cancer." (PMID 19649254, 2009). "Growing evidence suggests the presence of methylation in GATA4 gene promoter regions in gastric, esophageal, and ovarian cancers." (PMID 36588538, 2022). "Loss of this tumor suppressor gene expression has been connected to certain ovarian cancer subtypes in several studies: serous, clear cell and endometrioid ovarian cancers, while mucinous ovarian cancer expresses GATA4." (PMID 31744494, 2019). "Previously, the loss of GATA4 and GATA6 in ovarian cancer and epithelial cells was demonstrated to be by the mechanism of hypoacetylation of histones H3 and H4 and loss of histone H3/lysine K4 trimethylation at their promoters." (PMID 19649254, 2009). "GATA4 and GATA6 were found to be frequently lost in ovarian cancer, and the loss is proposed to account for dedifferentiation of the cancer cells." (PMID 19649254, 2009). "One striking feature of GATA4 and GATA6 staining is that though GATA4 and GATA6 are lost in most ovarian cancer (predominantly serous subtype), carcinomas of the mucinous subtype are mostly GATA4- and GATA6-positive." (PMID 19649254, 2009). "The loss of GATA4 precedes the loss of GATA6 (and Dab2), similar to the observation in the pre-neoplastic ovarian epithelia adjacent to ovarian carcinomas, where GATA4 is often lost prior to GATA6." (PMID 19649254, 2009). "Oncogenic SIRT7 could also suppress GATA4 transcriptional activity and activate the Wnt signaling pathway in ovarian cancer." (PMID 37691108, 2023). "Several publications indicate that a high level of GATA4 expression is associated with various outcomes dependent on cancer type; for example, a survival analysis indicated that a high GATA4 expression level is significantly correlated with better OS in second clinical-stage ovarian cancer." (PMID 37372326, 2023). "Besides the normal development function, GATA4 was reported as a potential tumor suppressor of colorectal cancer, lung cancer and ovarian cancer." (PMID 26625313, 2016). "Moreover, recent studies indicated an oncogene function of GATA4 in cancer, including gastric carcinoma, breast carcinoma and ovarian cancer." (PMID 26625313, 2016). "Furthermore, methylation of GATA4 is significantly higher in the ovarian cancer group compared with the control group." (PMID 26490736, 2015). "Increased promoter methylation of GATA4 has been shown in epithelial ovarian cancers." (PMID 24687970, 2014).
ovarian carcinoma (continued). "The GATA4 promoter is hypermethylated in cancer and it is involved in ovarian cancer." (PMID 24934728, 2014). "GATA4 and GATA6 are often lost in ovarian cancer cells, and it is speculated that the loss of these developmentally important transcription factors may be the underlying mechanism of dedifferentiation." (PMID 19649254, 2009). "The analysis revealed that many of the embryonic and cell development genes are fairly high expressed in ovarian cancer including FOXL2, GATA4, NR5A1, AMHR2, MAL and WIPF3." (PMID 31744494, 2019). "We further investigated the expression of GATA4 and GATA6 in ovarian surface epithelial lesions and histological subtypes of ovarian carcinomas by immunostaining." (PMID 19649254, 2009). "The finding of the loss of GATA4 at the very early, non-phenotypic stage preceding ovarian surface epithelial tumorigenesis may provide insight to the risk factors and initial step in the development of ovarian cancer." (PMID 19649254, 2009). "In ovarian cancer, methylation-specific PCR revealed GATA4 promoter methylation in 31.3 % (21/67) of specimens with ovarian cancer, and in none of the control ovarian tissue samples." (PMID 26490736, 2015). "Expression of GATA4 and GATA6 in ovarian cancer histological subtypes." (PMID 19649254, 2009). "Over the last 5 years in the studies of GATA factors in ovarian surface epithelial and culture cells, we found that GATA4 is absent in most ovarian cancer cell lines and also SV-40-transfected, “immortalized” ovarian surface epithelial cells." (PMID 19649254, 2009). "RNA sequencing of ovarian carcinoma-TA-MSCs identifies a distinct predictive algorithm comprising six genes: Annexin A8-like protein 2 (ANXA8L2), Collagen Type XV Alpha 1 Chain (COL15A1), Cytokine Receptor Like Factor 1 (CRLF1), GATA Binding Protein 4 (GATA4), Iroquois Homeobox 2 (IRX2), and TGF‐β2." (PMID 40676710, 2025). "IRF4, GATA4, GATA3, CIITA, and MYH11 were involved in the immune regulatory network, indicating that these five transcription factors might play a role in the immune microenvironment of ovarian cancer." (PMID 34109184, 2021). "Negative GATA6 and positive GATA4 exist only in rare cases of ovarian carcinomas." (PMID 19649254, 2009). "Both GATA4 and GATA6 proteins are expressed in ovarian surface epithelial cells but absent in most ovarian cancer cells." (PMID 19649254, 2009). "Previously, both GATA4 and GATA6 were observed to be strongly expressed in primary ovarian surface epithelial cells but absent in cultured ovarian cancer cells by both Western blot to examine the protein or Northern blot to measure mRNA." (PMID 19649254, 2009). "While GATA4 and GATA6 staining are absent or greatly reduced in most ovarian carcinomas." (PMID 19649254, 2009).
breast carcinoma (20 papers, 2006 to 2025). "Existing clinical data indicate that GATA4 seems to exhibit association with breast cancer progression, though the exact molecular mechanism remains to be defined." (PMID 38653973, 2024). "In CN loss genes, GATA4 is related to the progression of breast carcinoma from early stages and is an independent prognostic factor for survival in breast cancer-specific disease-free IDC patients." (PMID 28415743, 2017). "Expression levels of GATA4 have been linked to breast cancer progression." (PMID 32612205, 2020). "In breast cancer, GATA4 has been shown to act as a tumor suppressor by inhibiting invasion and migration, partly through the downregulation of MMP9 expression." (PMID 41226688, 2025). "Especially as the expression of GATA4 in breast cancer inversely correlates with the adverse prognostic marker ERBB2." (PMID 38653973, 2024). "Through bioinformatics and clinical data, it appears that GATA4 plays a role in breast cancer development." (PMID 38653973, 2024). "Given these insights, the GATA4/p65/HDAC1 complex emerges as a promising therapeutic target for breast cancer." (PMID 38653973, 2024). "In summary, our research unveils a novel mechanism wherein GATA4 curtails breast cancer cell metastasis by downregulating MMP9 expression, suggesting a potential therapeutic avenue for breast cancer metastasis." (PMID 38653973, 2024). "Supporting this, immunohistochemistry has shown that GATA4 status serves as a potential prognostic indicator for patient survival, pointing to GATA4’s possible influence on breast cancer progression." (PMID 38653973, 2024). "Our insights into the unique molecular interplay of the GATA4/NF-κB/MMP9 pathway shed new light on potential therapeutic avenues for breast cancer." (PMID 38653973, 2024). "This analysis showed that GATA4 expression was elevated in certain tumors, including breast cancer, prostate adenocarcinoma, and thyroid carcinoma, compared to their adjacent normal tissues." (PMID 38653973, 2024). "By analyzing clinical breast cancer samples from TCGA, we discerned the downregulation of GATA4 in metastatic breast cancer tissues." (PMID 38653973, 2024). "Nevertheless, the molecular mechanisms detailing GATA4’s effect on breast cancer metastasis remain largely uncharted." (PMID 38653973, 2024). "In our research, we revealed that GATA4 inhibits the invasion and migration of breast cancer cells by downregulating MMP9 expression." (PMID 38653973, 2024). "In conjunction with our prior molecular mechanism analysis and validation, these findings compellingly argue for GATA4’s role in curtailing breast cancer metastasis." (PMID 38653973, 2024). "Concurrently, GATA4’s role in regulating ERα-mediated transcription highlights a potential link with breast cancer progression." (PMID 38653973, 2024). "In this study, we identify GATA4 as a tumor suppressor in the invasion and migration of breast cancer." (PMID 38653973, 2024). "Our research asserted that GATA4 mitigates breast cancer cell metastasis through the downregulation of MMP9 transcription." (PMID 38653973, 2024). "Diving deeper into breast cancer, our analysis revealed that GATA4 mRNA levels were notably higher in breast carcinoma tissues compared to normal tissues and similarly in breast cancer paired tissues." (PMID 38653973, 2024). "In summation, our findings elucidate a novel interplay in breast cancer cells, where GATA4 curtails the influence of the p65/p50 complex on MMP9 expression by interacting with p65." (PMID 38653973, 2024). "In breast cancer, one of the top three ranked transcriptional regulators for both basal and luminal breast cancer’s down-regulated gene sets is GATA4." (PMID 33778495, 2021). "The central genes of the network were identified and RUNX1, PAX3, GATA4 and DLX5 genes were subjected for epigenetically dysregulation in association with diversity of breast cancer subtypes." (PMID 28747748, 2017).
breast carcinoma (continued). "The central genes of the network (RUNX1, PAX3, GATA4 and DLX5) were subjected for epigenetically dysregulation in association with different breast cancer subtypes." (PMID 28747748, 2017). "For example, L1CAM, GATA4, CCNB1, CDKN1C, and FEN1 have been reported for their association with breast cancer: L1CAM was shown to inhibit the growth of breast carcinoma cells." (PMID 18237428, 2008). "Similarly, evidence from in vitro and in vivo experiments in breast cancer revealed that GATA4 again functions as a tumor suppressor, demonstrating inhibitory effects on breast cancer cell proliferation and migration while promoting apoptosis." (PMID 39456519, 2024). "Earlier studies have intimated that GATA4 downregulates the expression of EMT markers in breast cancer cells, it’s plausible that GATA4 might be a significant inhibitor of EMT during breast cancer metastasis." (PMID 38653973, 2024). "This research accentuates GATA4’s role in curtailing breast cancer metastasis, offering fresh insights into GATA4’s tumor suppressive function during breast cancer progression, and underscores its potential as a therapeutic focal point for metastatic breast cancer." (PMID 38653973, 2024). "To further delve into this hypothesis, we firstly assessed GATA4’s expression in various breast cancer cell lines." (PMID 38653973, 2024). "This underpins GATA4’s role in thwarting breast cancer metastasis." (PMID 38653973, 2024). "Concurrently, we established that GATA4 impedes breast cancer cell invasion and metastasis." (PMID 38653973, 2024). "However, our analysis of breast cancer patients in the TCGA database showed that the expression level of GATA4, a tumor suppressor, was higher in carcinoma than in adjacent tissue, and this phenomenon was also observed in pancreatic cancer." (PMID 38653973, 2024). "Yet, the specific roles and mechanisms of GATA4 in breast cancer progression remain elusive." (PMID 38653973, 2024). "Prior research highlighted GATA4’s potential to reduce MMP2 expression in breast cancer cells." (PMID 38653973, 2024). "Mice model validated GATA4’s inhibitory stance on breast cancer cell metastasis." (PMID 38653973, 2024). "Moreover, the variation of GATA4 expression among breast cancer subtypes was analyzed by UALCAN, and this analysis showed that GATA4 expression tends to be lower in subtypes with more malignant character." (PMID 38653973, 2024). "Our research revealed the inhibitory effect on breast cancer of GATA4 via NF-κB pathway." (PMID 38653973, 2024). "Previously, GATA4 was identified as a tumor suppressor in breast cancer." (PMID 38653973, 2024). "Given that MMP2 and MMP9 play important roles in degrading type IV collagen with MMP9 being particularly influential in breast cancer metastasis, we sought to determine if GATA4 might also counteract breast cancer metastasis by modulating MMP9." (PMID 38653973, 2024). "Consequently, our data support the idea that GATA4 acts as a suppressor of breast cancer cell migration and invasion." (PMID 38653973, 2024). "GATA4’s influence extends to more than just MMP9 in breast cancer." (PMID 38653973, 2024). "We developed lentiviral vectors to induce the expression of mouse Gata4 (hereafter tet-Gata4) or a control cDNA encoding GFP (hereafter tet-GFP) and infected B16 murine melanoma cells, PyMT S2WTP3 murine breast cancer cells, and KP-derived primary murine lung adenocarcinoma cells." (PMID 35017504, 2022). "Moreover, GATA4 protein expression has been found to correlate positively with that of HER2 in breast cancer 45 and functional studies have shown that GATA4 directly binds HER2 promoter and regulates its expression." (PMID 24687970, 2014). "We further confirmed specificity of our findings to the colonic claudin-1 expression as similar transient overexpression of Cdx1, Cdx2 or GATA4 in human breast cancer cells (MCF-7) or renal epithelial cells (MDCK II cells) did not increase claudin-1 promoter activity." (PMID 22719836, 2012).
breast carcinoma (continued). "GATA4 was reported to regulate aromatase PII promoter activity in breast cancer cells." (PMID 18237428, 2008). "Additionally, we found that the transcription factors encoding GATA-4 and GATA-5 genes, whose promoter DNA is hypermethylated, were also re-expressed in both colon and breast cancer cells (unpublished data)." (PMID 16596166, 2006). "Thus, we believe that the differential expression of GATA4 across various breast cancer cell lines, and its regulated expression of MMP9, could contribute to intratumor heterogeneity." (PMID 38653973, 2024). "Therefore, we further analyzed whether the expression of GATA4 changes along with the progression of Tumor-Metastasis-Node stages in breast cancer." (PMID 38653973, 2024). "Collectively, this suggests that GATA4 might function as a metastatic regulator in breast cancer." (PMID 38653973, 2024). "Moreover, GATA4 hampers the metastasis of breast cancer in vivo mouse model." (PMID 38653973, 2024). "ERBB2 is a key regulator in breast cancer, and the strong negative feedback association between GATA4 and ERBB2 may contribute to the transcriptional dysregulation of ERBB2 gene expression in breast cancer." (PMID 30872657, 2019). "Given the critical role of MMP9 in breast cancer metastasis and the inhibitory effect of GATA4 on MMP9 transcription, we sought to further assess the influence of GATA4 on breast cancer metastasis." (PMID 38653973, 2024). "Our findings highlight GATA4’s inhibitory on MMP9 and delve into its unique mechanism in counteracting breast cancer invasion and metastasis." (PMID 38653973, 2024). "Prior research has highlighted GATA4’s capability to reduce MMP2 and MMP3 expression in breast cancer." (PMID 38653973, 2024). "To pinpoint GATA4’s function in breast cancer metastasis, we conducted cell scratch wound-healing and transwell assays in MCF7 and T47D cells or MDA-MB-231 and HCC1187 cells to eliminate possible effects by different breast cancer subtypes." (PMID 38653973, 2024). "Studies have also shown that GATA binding protein 4 (GATA4) recruits histone deacetylase, resulting in reduced acetylation of the transcription factor p65, thereby inhibiting p65 binding to the MMP9 promoter, inhibiting the transcriptional activity of MMP9, and preventing breast cancer metastasis." (PMID 40665344, 2025). "The expression of GATA4 did not have a significant correlation with the survival of breast cancer patients as expected, so we speculated that GATA4 is a potential metastatic marker in breast cancer." (PMID 38653973, 2024). "Further, our finding that similar overexpression of Cdx1, Cdx2 or GATA4 in the renal epithelial and breast cancer cells had no apparent effect upon claudin-1 expression suggest that this is not a universal mechanism of claudin-1 expression and is rather colon specific." (PMID 22719836, 2012).